BAP1 (BRCA1 associated deubiquitinase 1)
Diseases named in the same sentence as BAP1 in open-access papers (continued):
Sharing a sentence is not in itself a finding about the gene and the disease.
tumor (continued). "As only two of the BAP1-negative tumours demonstrated normal 8q, we cannot conclude on the effect of 8q gain within BAP1-negative lesions." (PMID 31337000, 2019). "Our analysis of molecularly defined tumor subgroups revealed that the prognostic impact of BAP1 was almost entirely driven by the ERG negative subset." (PMID 31903168, 2019). "In a multivariate model with the addition of either chromosome 3 or BAP1 status, tumour size also did not relate significantly to HIF1a expression." (PMID 31323773, 2019). "Although we have provided evidence that mechanisms can be shared between different malignancies, it remains to be determined whether BAP1 and KDM6A alterations are promoting tumour growth in SPNs through a similar epigenetic mechanism." (PMID 30306561, 2019). "Finally, the protein levels of ASXL2, BAP1 and UBE2E enzymes are highly correlated in mesothelioma tumors suggesting the importance of this signaling axis for tumor suppression." (PMID 30349006, 2018). "Additionally, BAP1 CNV was demonstrated using ddPCR and was correlated between tumor and cell-line samples." (PMID 30301262, 2018). "Precision medicine analysis of the tumor revealed two genomic alterations (BAP1 splice site 1729 + 1 G > A and PBRM1 N258fs*6) for which no targeted drugs or clinical trials were available." (PMID 29440675, 2018). "Immunohistochemical data indicated that BAP1 was scored as a negative or weak expression in 53.7% (115/214) of tumor tissues, as compared with only 33.2% (71/214) in corresponding adjacent normal intrahepatic biliary tissues." (PMID 30305612, 2018). "This prompted us to examine whether the remaining major tumor suppressors in ccRCC, SETD2 and BAP1, also regulate ISGF3 in VHL-/-ccRCC cells." (PMID 30355451, 2018). "Surprisingly, considering its role in a Polycomb complex, no transcriptional signature was consistently found among BAP1-inactivated tumor types." (PMID 29069806, 2017). "Research in the mechanism of miR-31 found that it could target genes such as ARID1A, SATB2, ARID1A, HuR, BAP1, EZH2, and RASA1, and it could further activate oncogenes and promote tumor cell proliferation, migration and invasive capability in vitro." (PMID 28404921, 2017). "In this case all neoplastic cells in both the TMA and several whole sections of tumour demonstrated negative staining for BAP1 in the presence of an internal positive control." (PMID 26982343, 2016). "In addition, the functions of BAP1 and KLF5 are similar in terms of promoting cell cycle progression, migration, tumour growth and lung metastasis." (PMID 26419610, 2015). "Immunohistochemically, the rhabdoid cells were positive for vimentin, whereas the tumor cell nuclei were mostly negative for BAP1." (PMID 25588411, 2015). "The tumor with the most mutated genetic landscape contained a shared SETD2 mutation and four nonshared mutations (in genes KDM5C, BAP1, and PBRM1)." (PMID 25124064, 2014). "Further work is needed to clarify the precise mechanism of action of BAP1 and HCF-1 in tumor suppression, which may vary depending on context and cell type." (PMID 23915344, 2013). "Although the directs targets of BAP1 have not been fully elucidated, other melanocyte-specific tumor proteins, such as MITF, have been shown to be regulated by another deubiquitinating enzyme, named ubiquitin-specific protease 13 (USP13)." (PMID 22545102, 2012). "Additionally, BAP1 gene testing is advisable for younger patients lacking asbestos exposure history and familial tumor aggregation." (PMID 40904706, 2025). "However, the critical role of BAP1 as a tumor suppressor in PM remains incompletely understood, and BAP1 is not fully implemented as a clinical prognostic or predictive biomarker yet." (PMID 40361508, 2025).
tumor (continued). "Finally, a single-center analysis including a systematic review and meta-analysis confirmed that BAP1 expression is not an independent prognostic factor for PM patients and should not be considered without considering tumor histology." (PMID 40361508, 2025). "Upon clinicopathological analysis, overexpression of BAP1 at mRNA level was significantly correlated with a more aggressive tumor behavior, with absence of tumor encapsulation (P = 0.030) and presence of tumor microsatellite formation (P = 0.049), which is a feature of intrahepatic metastasis." (PMID 39984455, 2025). "This variability suggests that BAP1 loss alone may not be sufficient to predict PITAC responsiveness, and other factors, such as tumor histology, immune microenvironment, or prior treatments, may contribute to the observed heterogeneity in outcomes." (PMID 40559230, 2025). "When considering the immuno-suppressive microenvironment in BAP1-negative UM, it may be necessary to use a high dose of Bel-sar or multiple treatments to induce total tumor ablation." (PMID 39911685, 2025). "Regarding the genomic profile of our patient’s tumor, the absence of identified mutations in BAP1, coupled with the patient’s solitary neoplasm and the absence of a family history of BAP1-related tumors, make it highly unlikely that the origin of her tumor was constitutional." (PMID 39091916, 2024). "In both tumor and liquid biopsies, we identified an increased frequency of alterations in genes involved in genome integrity or chromatin remodeling, including ARID1A (15%), PBRM1 (9%), and BAP1 (14%), which were validated using an in-house-developed immunohistochemistry panel." (PMID 38191492, 2024). "Compared with their BAP1 knockdown assays, we have tons of results indicated that shRNA mediated knockdown inhibit BE2C and SH-EP Tet21/N cells proliferation, migration, invasion, colony formation and tumor growth in the subcutaneous and orthotopic xenograft mice models." (PMID 37543638, 2023). "In addition, the tumor suppressor BAP1 decreases H2Aub occupancy on the SLC7A11 promoter and represses SLC7A11 expression in a deubiquitinating-dependent manner, that is, BAP1 inhibits cystine uptake by repressing SLC7A11 expression, leading to elevated lipid peroxidation and ferroptosis rates." (PMID 37580393, 2023). "KN-93 administration did not reduce the tumor growth of BAP1-WT MSTO-211H cells." (PMID 37479714, 2023). "Similarly, MITF was lower in tumours with chromosome 8q gain/amplification compared to UMs with normal 8q status (p = 0.02), as well as in tumours with negative BAP1 IHC staining compared to BAP1-positive tumours (p = 0.002)." (PMID 37240204, 2023). "But the exact function of BAP1 as intrinsic oncogene or tumor suppressor is not fully understood." (PMID 37543638, 2023). "The detection of isoechoic or hypoechoic tumours is more challenging, and whilst there are currently no data available regarding whether BAP1 tumours are hyperechoic, MRI could be considered as the preferred surveillance modality." (PMID 37607989, 2023). "As we have shown in our analyses, tumours with high MITF and low MITF are genetically different, and MITF expression has an inverse correlation with genetic negative prognostic factors such as monosomy 3, BAP1 loss, and chromosome 8q gain." (PMID 37240204, 2023). "Importantly, although spXmm66 is derived from a BAP1+/non-monosomy 3 (D3) tumor it highly expresses GPX4, explaining its strong response to RSL3." (PMID 37321991, 2023).
tumor (continued). "Interestingly, none of VHL, SETD2, PBRM1 and BAP1 is indicated in these marker gene lists suspecting a missing link between the well-known DNA tumour markers and the actual behaviour of tumour cells." (PMID 35586183, 2022). "Although there is no functional proof that FOXD1 and BAP1 interact, due to the distinct FOXD1 expression pattern in UM it might be involved in diverting from a low-risk to high-risk tumor." (PMID 35954332, 2022). "Analysis of BAP1-TPDS tumor genomes has never been thoroughly performed." (PMID 35885614, 2022). "Furthermore, relevance analyses of clinical data in PCa and many other cancers revealed a significant positive correlation between BAP1 and PTEN at the protein level, indicating that the BAP1‐PTEN signaling axis might play important roles in tumor suppression." (PMID 33155366, 2021). "Interestingly, 1 patient appearing to have no BAP1 alteration in his tumor (using GPS CancerTM) had a family history of MPM in two brothers." (PMID 33777745, 2021). "The mean volume of all tumor cells regardless of BAP1 expression was 2105 μm3 (SD 936)." (PMID 33903674, 2021). "In regression analysis, the difference in BAP-1 expression between hot spots and cold spots could was not a function of tumor volume." (PMID 33800007, 2021). "No tumor presented concomitant variants in GNAQ/GNA11 and in SF3B1 or BAP1." (PMID 34359736, 2021). "Moreover, if we adjusted the Cox regression models additionally for tumor size and BAP1, the results did not alter (data not shown)." (PMID 34830810, 2021). "The mutations found in BAP1-TPDS patients affect ubiquitin carboxyl hydrolase (UCH) and nuclear localization signal (NLS) domains and create a non-functional truncated protein, disrupting BAP1 deubiquitinating activity and nuclear localization, both required for BAP1 tumor suppressor function." (PMID 35008179, 2021). "Except for one tumor (patient 4), all primary tumors were BAP1 negative." (PMID 34885018, 2021). "This is likely not the case, as we found BAP1 expression is a function of tumor volume." (PMID 33903674, 2021). "Molecular alterations in RCC tumors have been extensively studied in the last decade, especially in ccRCC but neither identified mutations (e.g.,: VHL, BAP1, PBRM1, SETD2, KDM5C, MTOR) nor transcriptome-based ccRCC tumor sub-classification have straightforward clinical relevance." (PMID 33535553, 2021). "The same analysis was performed in a sub-cohort including only tumor tissues; the positive correlation trends were confirmed, but the p-values were not significant (LINC00518 vs. MET: r-value = 0.31, p-value = 0.12, LINC00518 vs. BAP1: r-value = 0.35, p-value = 0.06)." (PMID 33371395, 2020). "The deubiquitination of histone H2A on lysine 119 by 2A-DUB/MYSM1, BAP1, USP16, and other enzymes is required for key cellular processes, including transcriptional activation, apoptosis, and cell cycle control, during normal hematopoiesis and tissue development, and in tumor cells." (PMID 32466590, 2020). "Regardless of whether the patient has co-occurring VHL and BAP1 mutations or co-occurring VHL and PBRM1 mutations, T cell activation genes form coordinated co-expression in the tumor." (PMID 30814637, 2019). "Combined, this strongly indicates that PeM could be divided into tumors with an inflammatory tumor microenvironment and those without and that this distinction correlated with BAP1 haploinsufficiency." (PMID 30777124, 2019). "Similarly, within the set of M3 tumours, BAP1-negative tumours (n = 27) had a higher expression of HIF1a compared to BAP1-positive tumours (n = 7) (p = 0.015)." (PMID 31323773, 2019). "Irrespective of the underlying mechanism, the selective prognostic impact of BAP1 in ERG negative cancers demonstrate, that the applicability (and perhaps thresholds) of prognostic markers may depend on individual molecular tumor features." (PMID 31903168, 2019).
tumor (continued). "Furthermore, results of functional assays indicated that BAP1 controlled ICC cell proliferation, cell cycle progression, and invasion in vitro, as well as tumor progression in vivo, by modulating the extracellular signal-regulated kinase 1/2 (ERK1/2) and c-Jun N-terminal kinase (JNK)/c-Jun pathways." (PMID 30305612, 2018). "BAP1 IHC was possible in 10 cases, a single case had no remaining available tumour material." (PMID 30558566, 2018). "Since the suppression of PBRM1, KDM5C, SETD2 or BAP1 all lead to the reduction of ISGF3, a potent tumor suppressor, it is possible that any effective therapeutic intervention that restores ISGF3 function could benefit ccRCC patients with a wide variety of mutations." (PMID 30355451, 2018). "Low BAP1 expression was significantly correlated with high serum CA19-9 level (P = 0.001) and aggressive tumor characteristics, such as larger tumor size (P = 0.010), presence of lymphatic metastasis (P < 0.001), and advanced tumor node metastasis (TNM) stage (P = 0.005)." (PMID 30305612, 2018). "Nuclear BAP1 (nBAP1) expression was noted in the tumour cells in eight cases and was absent in two." (PMID 30558566, 2018). "BAP1-wild-type tumours showed no response to rTRAIL compared with vehicle." (PMID 29345617, 2018). "The nature of the apparent selective advantage of monosomy or isodisomy over the simple deletion of the wild-type copy of BAP1 and the reason why BAP1 did not consistently show up in the cytogenetics-based tumor suppressor gene research is unknown." (PMID 28229253, 2017). "Here we show that cells from BAP1+/− carriers do not need to go through a selection process that favors the emergence of clones with a Warburg effect required for tumor growth: normal primary BAP1+/− cells constitutionally derive a large part of their energy through aerobic glycolysis." (PMID 28665402, 2017). "Moreover, RNA-seq data from each of 40 advanced PDAC tumor specimens from the TCGA data base indicate a negative correlation between expression of miRNA-125b and five of six potential target genes (BAP1, BBC3, NEU1, BCL2, STARD13)." (PMID 25184537, 2014). "However, we now show that this effect is not sustained in cells that are stably depleted of BAP1, implying that this initial growth defect is not a critical factor in BAP1’s role as a tumor suppressor." (PMID 23915344, 2013). "This suggests that BAP1 might not regulate tumor immunity by affecting the expression of PD-L1." (PMID 39350280, 2024). "Finally, we examined the effect of KN-93 on the tumor growth of BAP1-negative MMe cells in vivo." (PMID 37479714, 2023). "Moreover, tumor suppressor factor BAP1, an epigenetic regulator, has also been shown to downregulate SLC7A11 expression to promote ferroptosis, but the extent of BAP1’s pro-ferroptotic activity in tumor suppression remains unclear." (PMID 38562992, 2023). "Finally, to evaluate the potential clinical relevance of BAP1 targeted genes in patient samples, we retrieved the RNA-seq data from both normal lung tissues (n = 7) and SCLC patient tissues (n = 79) and further isolated the genes that are significantly dysregulated in tumor samples." (PMID 35194152, 2022). "However, this reclassification may have been biased by the use of a forward primer mapping on exon 9—which is therefore not suitable to identify exon 9 skipping—when sequencing BAP1 transcript from tumor specimens." (PMID 35885614, 2022). "However, the topological data suggested that these eQTLs might represent tissue-specific regulatory associations not present in HMEC, and that if the rs57025206-related survival effect is mediated via BAP1 or MIR135A, it probably reflects host–tumor interactions." (PMID 32964118, 2020).
tumor (continued). "Notably, when STRING network analysis was used to investigate functional interactions, this revealed a DDR cluster that included BRCA1 and BRCA2, as well as their interacting tumour suppressor partners PALB2 and BAP1, two cancer-associated DDR genes not previously indicated as G4 ligand sensitisers." (PMID 31287417, 2019). "Wild-type BAP1, but not mutant BAP1, significantly inhibits the proliferation, invasion, EMT of HCC cells in vitro, and tumor progression and metastasis in vivo." (PMID 40607251, 2025). "In particular, studies on UM have identified aqueous and vitreous humor as sources of circulating tumor DNA, but no studies have been specifically conducted on GNAQ, BAP1, SF3B1, and EIF1AX related proteins." (PMID 38175637, 2024). "We now show a relation with the genetic status of the tumour: tumours with monosomy 3, on average, had a lower MITF expression than tumours without monosomy 3, as did tumours with negative BAP1 IHC staining compared to UMs with positive BAP1 IHC staining." (PMID 37240204, 2023). "For example, gene expression class, BAP1, SF3B1, EIF1AX, and chromosome 3 status, presence or absence of vasculogenic mimicry, and tumor cell type are all important prognostic factors that were not accounted for herein." (PMID 36398623, 2023). "The tumor cells were positive for AE1/AE2, calretinin, WT-1, D2-40, HEG1, EMA, BAP1, and MTAP and negative for carcinoembryonic antigen, MOC-31, Ber-Ep4, ER, PgR, TTF-1, claudin 4, and desmin." (PMID 36896044, 2023). "In conclusion, latitude appears to be a prognostic factor in UM, independent of patient age, sex, tumor diameter, tumor thickness, AJCC T-category, BAP-1 expression, to the quantity of sunlight or UV, or to temperature." (PMID 36310339, 2022). "Moreover, we confirmed the establishment of an epigenetic dynamic interplay between the BAP1/ASXL3 complex and the opposing ncPRC1 complex, which could potentially be targeted for developing other therapeutics in order to increase the effectiveness against SCLC tumor progression." (PMID 35194152, 2022). "This–together with the finding that BAP1 mutation rates were significantly higher, and BAP1 mutations almost exclusively present, in HBV RNA negative tumors–suggests that BAP1 mutant HCC could represent an HCC subtype characterized by lack of HBV activity in tumor and improved outcomes." (PMID 33561166, 2021). "While the combination of BAP1 deletion with GNAQ11Q209L yielded larger cutaneous melanocytic lesions, there was no such observed effect in UM tumours." (PMID 34149931, 2021). "mUMs were assessed for morphology, nuclear BAP1 (nBAP1) expression, and their tumour microenvironments (TME) using an “immunoscore” (absent/altered/high) for tumour-infiltrating lymphocytes (TILs) and macrophages (TAMs)." (PMID 33008022, 2020). "Other signalling pathways significantly deregulated in AFP-high tumours and worthy of further analysis include IGF2–IGFR, mTOR, NOTCH and BAP1." (PMID 31285588, 2019). "Overexpression of wild-type but not mutant BAP1 significantly suppressed ICC cell proliferation, cell cycle progression, and invasion in vitro, as well as tumor progression in vivo." (PMID 30305612, 2018). "However, the critical roles of BAP1 as a tumor suppressor in MPM remain incompletely understood, and utilization of BAP1 status for therapeutic stratification has not yet been realized." (PMID 36669126, 2023). "Since entinostat enhanced TIL killing also of the BAP1 mutant cell line UM22, it may reflect that the BAP1 status may not impact on a tumor-intrinsic property but on an effect of the TME." (PMID 34753889, 2022).